KL (klotho)
Diseases named in the same sentence as KL in open-access papers (continued):
Sharing a sentence is not in itself a finding about the gene and the disease.
type 1 diabetes (16 papers, 2013 to 2025). "Microalbuminuria was proven to be associated with serum soluble Klotho deficiency in patients with type 1 diabetes in a cross-sectional single-center study." (PMID 36675565, 2023). "Further studies are required to determine whether soluble Klotho is causally related to the development of cardio-renal disease in type 1 diabetes." (PMID 28194484, 2017). "In individuals with type 1 diabetes, microalbuminuria is associated with soluble Klotho deficiency." (PMID 28194484, 2017). "The present study showed that soluble Klotho concentration was significantly lower in pediatric patients with type 1 diabetes compared to healthy individuals, especially in those with the worst metabolic control, expressed as high HbA1c levels." (PMID 34603200, 2021). "A nephroprotective role has been demonstrated for Klotho in an animal model of type 1 diabetes, with global overexpression ameliorating the histological features of DKD and reducing albuminuria." (PMID 28194484, 2017). "Soluble Klotho levels reported in healthy adults, measured with the same assay used in the present study, are similar to our findings in individuals with type 1 diabetes." (PMID 28194484, 2017). "This is the first study to demonstrate that individuals with type 1 diabetes and MA+ have significantly lower serum soluble Klotho levels compared with MA− individuals." (PMID 28194484, 2017). "Previous studies in hyperlipidemic rats with non-insulin-dependent diabetes or hypercholesterolemic uremic atherosclerotic ApoE KO mice reported a decreased renal klotho gene expression." (PMID 24386260, 2013). "Similarly, circulating levels of s-Klotho are frequently depressed in both type 1 diabetes (T1D) and type 2 diabetes (T2D)." (PMID 39272986, 2024). "However, still little is known on the alteration of Klotho levels in people with type 1 diabetes, as data on Klotho concentration in this group, especially children, are scarce." (PMID 34603200, 2021). "Klotho may be a potential target to reduce or significantly slow the progression of renal disease in individuals with type 1 diabetes." (PMID 28194484, 2017). "In rodent models of type 1 diabetes, renal expression of Klotho is reduced." (PMID 28194484, 2017). "In the study subcohort we noted significantly lower levels of circulating Klotho in the MA+ group and this may suggest that changes in Klotho occur early in type 1 diabetes DKD and before overt changes in other markers of calcium and phosphorus metabolism." (PMID 28194484, 2017). "Moreover, there is a number of evidence that decrease in Klotho concentration may contribute to beta cell apoptosis and type 1 diabetes development." (PMID 34603200, 2021). "The role of soluble Klotho in patients with type 1 diabetes and microalbuminuria is unknown." (PMID 28194484, 2017). "Our results suggest that children with type 1 diabetes have significantly lower FGF19 and soluble klotho concentrations and higher VEGF concentrations compared to healthy individuals, especially in individuals with the worst metabolic control, being expressed as high HbA1c levels." (PMID 36927328, 2023). "This study reports the significantly lower level of s-Klotho in children with type 1 diabetes, correlated with HbA1c and HDL cholesterol, but not with the adhesion molecules concentrations nor the duration of the disease." (PMID 34603200, 2021).
Ureteral obstruction (16 papers, 2014 to 2024). Obstruction of the flow of urine through the ureter. "In various AKI rodent experiments including ischemia-reperfusion injury, cisplatin induced AKI and postrenal unilateral ureteral obstruction models, all indicate a systemic Klotho deficiency state, and applying Klotho supplement possess a considerable potential therapeutic effect." (PMID 38187354, 2023). "Studies have shown that HDAC3 is abnormally active in fibrotic kidneys caused by unilateral ureteral obstruction (UUO) and aristolochic acid nephropathy (AAN), and its deletion can promote the expression of klotho to fight against kidney fibrosis." (PMID 37362429, 2023). "Previous studies have revealed that a reduced expression level of klotho in the kidneys aggravates renal interstitial fibrosis in mice induced by unilateral ureteral obstruction." (PMID 25695625, 2015). "Previous studies have suggested that Klotho provides reno-protection against unilateral ureteral obstruction (UUO)-induced renal tubulointerstitial fibrosis (RTF)." (PMID 25297969, 2014). "Empagliflozin increased renal klotho expression in unilateral ureteric obstruction rat model." (PMID 35176041, 2022). "Animal studies have shown transient renal Klotho deficiency in AKI under a variety of conditions, including hypovolemia, nephrotoxins such as CDDP and folic acid, ischemia-reperfusion injury, lipopolysaccharides, and ureteric obstruction." (PMID 26799323, 2016). "Recent reports showed that Klotho plays an important role in modulating ER signaling crosstalk between autophagy and apoptosis and Klotho treatment alleviates ER stress in unilateral ureteral obstruction or attenuates oxidant-induced alveolar epithelial cell apoptosis." (PMID 31772699, 2019). "In models of unilateral ureteral obstruction (UUO), it was observed that hypermethylation of the Klotho promoter by TGFβ decreased Klotho protein expression, which led to tubular and interstitial fibrosis." (PMID 36232403, 2022). "Recent studies have shown that in adenine mice or unilateral ureteral obstruction (UUO) mice, rhein effectively recovered Klotho promoter hypermethylation via reversing aberrant DNA methyltransferases expression, thus upregulating the expression of Klotho protein." (PMID 35924053, 2022). "Exogenous Klotho expression suppressed the upregulation of AGT, renin, ACE, and AT1R protein expression and normalized blood pressure in 5/6 nephrectomised rats and unilateral ureteral obstruction (UUO) mice." (PMID 36059935, 2022). "A reduced renal klotho expression enhances the high levels of transforming growth factor-β1 (TGF-β1), α-smooth muscle actin (α-SMA), and fibronectin in mice after unilateral ureteral obstruction, which then worsens renal interstitial fibrosis." (PMID 32942691, 2020).
depression (15 papers, 2013 to 2025). "Recent literature suggests that the level of α-Klotho is regulated by chronic stress and depression, and polymorphisms of the Klotho gene affect the plasma level of α-Klotho in healthy individuals." (PMID 34721095, 2021). "Additionally, susceptible-specific regions that gained 5hmC were found in the klotho gene KI, which has been linked to chronic stress-induced depression through its modulation of the glutamate receptor subunit GluN2B." (PMID 37228107, 2023). "A better understanding of the mechanism underlying how Klotho-Nrf2- NF-κB induces antioxidant and anti-inflammatory effects may lead to the development of new pharmacological strategies for depression." (PMID 37894946, 2023). "Research on the significance of Klotho in depression is relatively rare (especially in animal studies), which is surprising given that depression is associated with accelerated cellular aging and aging-related phenotypes and comorbidities seen in Klotho deficiency." (PMID 37894946, 2023). "Thus, depression was linked with lower klotho levels, particularly in high-stress women with moderate to severe depressive symptoms." (PMID 26080320, 2015). "Klotho regulates the signaling pathways involved in the pathogenesis of depression (especially in relation to oxidative stress imbalance, inflammation, and glutamate neurotransmission)." (PMID 37894946, 2023). "The role of Klotho in the pathophysiology of depression, mainly in Glu neurotransmission, is not well understood." (PMID 37894946, 2023). "Conversely, lower circulating klotho levels are reported in bipolar disorder, depression, multiple sclerosis, temporal lobe epilepsy, AD and recently, PD." (PMID 36552155, 2022). "This threshold effect has been observed in the relationship between DII score and serum Klotho, sex hormones, and depression." (PMID 36687707, 2022). "Most human studies have focused on peripheral (serum) changes in Klotho levels in depression." (PMID 37894946, 2023). "However, the most-studied phenomenon in depression is changes in Glu neurotransmission; therefore, the next section will discuss this context with Klotho." (PMID 37894946, 2023). "Recently, it was postulated that Klotho may play a role in the antidepressant effects of ketamine in patients with treatment-resistant depression and suicidal thoughts." (PMID 37894946, 2023). "Confirmation of the hypothesis that Klotho may be related to the pathophysiology of depression comes from an increasing number of human studies that indicate changes in Klotho protein in the cerebrospinal fluid and blood." (PMID 37894946, 2023). "Genetic knockdown of the KL gene in the NAc resulted in depression-like changes in naïve mice." (PMID 37894946, 2023). "Clinical evidence shows that low levels of circulating KL are related to depression." (PMID 36674721, 2023). "It follows that the regulation of the Klotho protein by NMDA receptors may be a new strategy or molecular target for the pharmacological treatment of depression." (PMID 37894946, 2023). "Interestingly, a small exploratory study also found that CSF klotho levels are increased by electroconvulsive treatment for depression." (PMID 36552155, 2022). "As a previous report suggested that the lower level of α-Klotho is associated with more severe depression-like symptoms in healthy people under chronic stress, we speculated that the Klotho polymorphism might affect the elderly MDD patients via reducing plasma α-Klotho levels." (PMID 34721095, 2021). "Lower levels of klotho could contribute to stress and its maladaptive correlates such as depression by influencing a myriad of cellular and molecular targets." (PMID 26080320, 2015). "Mechanisms regulating glutamate cycling and metabolism including Klotho may be viable drug targets for depression and schizophrenia." (PMID 23923038, 2013).
depression (continued). "It is associated with NMDA-dependent neurotransmission, which is also involved in depression, but the mechanism may be different; therefore, in this subsection, we focus on Klotho’s involvement in cognitive changes in an attempt to understand the mechanism underlying its efficacy." (PMID 37894946, 2023). "In addition, Klotho is present in brain structures closely related to the pathophysiology of depression (including the hippocampus and cerebral cortex) and is essential in the regulation of oxidative and inflammatory processes (well-known pathological factors in depression)." (PMID 37894946, 2023). "This suggested that Klotho activation may have antidepressant and anxiolytic effects as it influences Glutamate [N-methyl-D-aspartate] receptor subunit 2B, which are crucial for synaptic function and plasticity in depression that are consistent with previous findings." (PMID 40351444, 2025). "Intersecting 87 targets predicted by network pharmacology for PPT for depression with 350 DEGs from transcriptome sequencing yielded a total of three target genes (TTR, FOS, and KL)." (PMID 39062817, 2024). "Our data suggest that PPT may achieve the treatment of depression by inhibiting the expression of FOS, enhancing the expression of TTR and KL, and modulating the PI3K-AKT signaling pathway." (PMID 39062817, 2024). "We concluded that PPT might be therapeutic in depression through the PI3K-AKT signaling pathway and unearthed three key targets (TTR, FOS, and KL)." (PMID 39062817, 2024). "Limited animal studies (particularly, animal models of depression) have demonstrated the lack of described molecular mechanisms that regulate Klotho in the central nervous system." (PMID 37894946, 2023). "In women without depression, there was a trend toward lower levels of klotho in high-stress women compared with low-stress women (P=0.079)." (PMID 26080320, 2015). "Importantly, defining the baseline level of Klotho in depression (independent of age) is needed." (PMID 37894946, 2023).
melanoma (15 papers, 2016 to 2025). A malignant, usually aggressive tumor composed of atypical, neoplastic melanocytes. "Human studies on oesophageal, ovarian cancer, and melanoma have shown that positive klotho expression is associated with improved survival and low metastatic rate." (PMID 35666743, 2022). "The results revealed that p-NF-κB and Klotho protein levels were independent predictors of poor overall survival, indicating that high p-NF-κB or low Klotho protein levels were significantly associated with poor overall survival in melanoma patients (p<0.05)." (PMID 27779100, 2016). "In addition, loss of Klotho leads to increased Wnt5A expression, filamin cleavage, and cell migratory potential during melanoma progression." (PMID 32614356, 2020). "Rosiglitazone inhibits melanoma resistance by increasing serum levels of klotho and decreasing levels of Wnt5A in the blood and tumor microenvironment of mice." (PMID 40134808, 2025). "Curiously, we noticed an increase in the mRNA level for KL in melanoma cells treated with 1,25(OH)2D3 alone (p < 0.01) or in combination with tested FGFR inhibitors in comparison to inhibitors alone." (PMID 38473753, 2024). "Klotho (KL) is a potent tumor suppressor in many malignancies, including colorectal, glioma, melanoma, and ovarian cancers." (PMID 35468874, 2022). "Treatment of melanoma cells with media of aged fibroblasts results in increased Wnt5a expression and less KL mRNA expression, compared to incubation with media of young fibroblasts." (PMID 33520985, 2020). "In different melanoma cell lines, a mutually inhibitory effect of Wnt5a and KL expression is established impacting on metastasis." (PMID 33520985, 2020). "Klotho can inhibit internalization and signaling of Wnt5A, which drives melanoma metastasis and resistance to targeted therapy." (PMID 33373316, 2020). "KL expression in melanoma cells is enhanced by PPARγ, and KL or PPARγ agonist rosiglitazone treatment reduce melanoma growth in mice." (PMID 33520985, 2020). "In conclusion, our study first proposed that inflammation inhibits Klotho gene expression in melanoma cells through activation of the inflammatory mediators Hmgb1 and NF-κB signal pathway." (PMID 27779100, 2016). "Positive Klotho protein staining was observed in 45% of melanoma tissues, which was significantly lower than that in black nevus carcinoma and peritumoral tissues (85%)." (PMID 27779100, 2016). "Knockdown of Klotho gene expression significantly decreased apoptosis, increased invasion in melanoma cells, and inhibited xenograft A375 tumor growth." (PMID 27779100, 2016). "The low Klotho protein expression correlated with high percentage of positive p-NF-κB staining in melanoma tissues." (PMID 27779100, 2016). "This study investigated the effects of Hmgb1 and LPS on Klotho gene expression in melanoma cells and their relationship with NF-κB signaling and the biological significance of inflammation-Klotho in the malignant phenotype of melanoma." (PMID 27779100, 2016). "Introduction of exogenous Hmgb1 significantly decreased apoptosis, increased invasion, elevated p-NF-κB, but lowered Klotho protein level in melanoma cells." (PMID 27779100, 2016). "Expressions of Klotho and WNT-5A are inversely correlated in melanoma tissues, whereas the presence of Klotho suppressed melanoma cell invasion." (PMID 26514730, 2016). "p-NF-κB and Klotho protein expression in melanoma tissues significantly correlated with the clinical stage (P<0.05)." (PMID 27779100, 2016). "In short, we found that Klotho gene expression in melanoma cells is inhibited by inflammatory factors NF-κB." (PMID 27779100, 2016). "This study found that Klotho protein expression was significantly lower in melanoma tissues than that in peritumoral tissues and black nevus tissues." (PMID 27779100, 2016). "Our study suggests a pathway of inflammation-activated NF-κB-Hmgb1-Klotho in the cell survival, proliferation, and tumor growth of melanoma." (PMID 27779100, 2016).
melanoma (continued). "Low Klotho protein expression significantly correlated with poor prognosis of patients with melanoma." (PMID 27779100, 2016). "In exogenous Hmgb1 treated cells, significant increas in p-NF-κB level, but decrease in Klotho protein expression, was observed in A375 and SK-28 melanoma cells." (PMID 27779100, 2016). "In conclusion, Hmgb1 can inhibit Klotho gene expression and malignant phenotype in melanoma cells through activation of NF-κB signaling." (PMID 27779100, 2016). "Furthermore, treatment of melanoma cells with recombinant Klotho has been shown to decrease the development of metastases." (PMID 32585905, 2020). "First, Wnt signaling can mediate age-related therapy resistant in melanoma through klotho." (PMID 33373316, 2020). "Moreover, KL inhibits Wnt5a-mediated filamin A cleavage through calpain, an effect contributing to reduced motility of melanoma cell lines." (PMID 33520985, 2020). "Increasing klotho levels may improve the therapeutic effect of BRAF inhibitors by targeting Wnt signaling in melanoma patients of advanced age." (PMID 33373316, 2020). "Melanoma cells exhibit KL expression, depending on the age of surrounding fibroblasts." (PMID 33520985, 2020). "HMG protein B1 (HMGB1) activates NF-κB and inhibits KL expression melanoma cell lines." (PMID 33520985, 2020). "In this study, 4 melanoma cell lines were used to screen Klotho and Hmgb1 protein expression." (PMID 27779100, 2016). "In addition, the Klotho gene is progressively lost in melanoma under an unknown mechanism." (PMID 27779100, 2016). "The highest quartile of Klotho had significant 34% lower odds of skin cancer (OR, 0.66; 95% CI, 0.45-0.96; P =.03) than the lowest quartile; the odds for melanoma were not significant (OR, 0.69; 95%CI, 0.36-1.33; P =.26)." (PMID 37752937, 2023). "A significantly high percentage of cells stained positive for p-NF-κB, but negative for Klotho, in melanoma tissues compared to normal and benign skin tissues." (PMID 27779100, 2016). "The positive p-NF-κB and negative Klotho protein expression correlated with poor prognosis in melanoma patients." (PMID 27779100, 2016). "In melanoma samples, a negative correlation of Wnt5A and Klotho expression has been observed." (PMID 32585905, 2020). "Animal studies have suggested that Klotho may protect against melanoma and nonmelanoma skin cancer." (PMID 37752937, 2023).